MST1 (macrophage stimulating 1)
Diseases named in the same sentence as MST1 in open-access papers (continued):
Sharing a sentence is not in itself a finding about the gene and the disease.
tumor (continued). "Mammalian sterile 20-like kinase 1 (Mst1) is a critical component of the Hippo signaling pathway, which regulates a variety of biological processes ranging from cell contact inhibition, organ size control, apoptosis and tumor suppression in mammals." (PMID 23527007, 2013). "Furthermore, in vivo experiments showed that MST1 knockout mice exhibited more aggressive BRAFV600E tumor phenotypes." (PMID 21249150, 2011). "Moreover, these tumours were usually seen after 12 months age, considerably later than in the Mst1/Mst2 null livers." (PMID 21102585, 2011). "However, Tg-BRAFV600E/MST1 null mice showed aggressive PTC tumor phenotypes compared with their Tg-BRAFV600E littermates." (PMID 21249150, 2011). "The Hippo signaling pathway is a highly conserved tumor suppressor pathway, mainly including Ste20-like kinase 1 (MST1) and large tumor suppressor 1 (LATS1), Yes associated protein 1 (YAP1) and its analog TAZ, and the regulatory subunits of MST1 and LATS1, MOB1 and SAV1." (PMID 35810157, 2022). "On a hard surface, the Hippo pathway is involved in the proliferation of tumor cells, consisting of three main components: large tumor suppressor 1/2 (LATS1/2), yes-associated transcriptional regulator/tafazzin (YAP/TAZ) and mammalian Ste20-like kinases 1/2 (MST1/2)." (PMID 35267698, 2022). "Therefore, we speculated that Apatinib could lessen the expression of oncogene YAP/TAZ, which in turn relieves the inhibition of the tumor suppressor genes MST1/2 and LATS1/2; they may also play roles at the same time in the process Apatinib works." (PMID 32849930, 2020). "Importantly, while wild type BRAF does not bind to MST1, the oncogenic mutant BRAFV600E can bind to this tumour suppressor, which could conceivably shut down the anti-oncogenic signal mediated by MST1/2 in several cancer types." (PMID 31963420, 2020). "Moreover, in M2 enriched PDAC patients, MST-1 induction towards WNT inhibition could represent a tool to circumvent the pro-tumor M2 addicted immune-suppressive environment." (PMID 31277479, 2019). "Mst1/2 can be activated by cellular stressors and the activation of Mst1/2 might enforce a feedback stimulation system to regulate oxidant levels through several mechanisms, in which regulation of cellular redox state might represent a tumor suppressor function of Mst1/2." (PMID 23985272, 2013). "Thus, loss of regulation upstream of Mst1/2 is a common abnormality in human HCC and may account for Yap activation in these tumours." (PMID 21102585, 2011). "Hence, the Mst1/Mst2-dependent inactivation of Yap is a critical tumour suppressor mechanism." (PMID 21102585, 2011). "Within the Hippo pathway, MST1/2 and LATS1/2 act as tumor suppressors by inhibiting PD-L1 expression, whereas the downstream effectors YAP and TAZ promote PD-L1 upregulation, thereby impairing T-cell function and facilitating immune escape." (PMID 41256331, 2025). "Studies on MST1 and MST2 show that these genes are effective in maintaining the size of organs and in tumor development." (PMID 40106220, 2025). "Genetic or pharmacological re‐expression of tumor suppressors within the Hippo pathway, including activating LATS1/2 kinases and MST1/2 (mammalian Ste20‐like kinases), has also been explored." (PMID 40895190, 2025). "By influencing the localization and activity of critical proteins such as MST1/2 and YAP, LLPS can alter the downstream effects of the Hippo pathway, thereby impacting tumor initiation and progression." (PMID 39757214, 2025). "Western blot analysis showed that RGD treatment increased the level of MST1/2, LATS1 and YAP phosphorylation but markedly reversed the elevated levels of FAK, SRC and AKT phosphorylation induced by VPS35 overexpression in tumour cells." (PMID 37950040, 2024). "Our research further elucidated the important role of STRN3, as a great component of STRIPAK itself in the dephosphorylation of MST1/2 and YAP in HCC, as well as its biological impact on tumour cell proliferation and migration." (PMID 38429901, 2024).
tumor (continued). "Further investigation revealed that lactate derived from CAFs negatively regulates the HIPPO pathway through the DLG5/CUL3/MST1 axis, thus promoting the nuclear localization of YAP1 and enhancing the tumor stem cell phenotype." (PMID 39605072, 2024). "The upstream components of the Hippo pathway, MST1/2 and LATS1/2, function as tumor suppressors by promoting the binding of YAP/TAZ and 14-3-3 through phosphorylation, leading to their cytoplasmic localization and degradation." (PMID 38499647, 2024). "The Hippo pathway consists of four tumor suppressors: SAV1, MST1/2, LATS1/2, and MOB kinase activators." (PMID 38920690, 2024). "Taken together, these results demonstrate that the overexpression of PDSS2-Del2 in HCC cells enhances MST1 secretion by expediting SKOR1 degradation, subsequently recruiting macrophages into the tumor microenvironment." (PMID 39695147, 2024). "MST1/2 activity is also regulated by heterodimerization with RASSF family proteins, which are tumor suppressors." (PMID 38920690, 2024). "The Hippo kinases MST1 and MST2 initiate a highly conserved signaling cascade called the Hippo pathway that limits organ size and tumor formation in animals." (PMID 38624208, 2024). "Moreover, compounds like carbenoxolone may also inhibit the Hippo pathway, indicating that a dual role depending on their context of use, targeting upstream regulators such as MST1/2 kinases, has emerged as a promising strategy to restore Hippo signaling and promote tumor suppression." (PMID 39595118, 2024). "A positive relationship between tumor YAP1 and TET1 levels was then validated in MST1/2−/− mouse tumor tissues and clinical HCC tissues." (PMID 38967794, 2024). "On the contrary, restoration of YAP1 expression by pharmaceutical inhibition of MST1/2 induced conversion of M2-to-M1-like polarized MФs, elevating the infiltration of CD8+ T cells and attenuating tumor growth." (PMID 39198883, 2024). "Previous studies have demonstrated that essential elements of the Hippo pathway, including MST1/2, LATS1/2, YAP/TAZ, and TEAD, play important roles in innate and adaptive immunity against tumor cells." (PMID 38499647, 2024). "MST1/2 and LATS1/2 have tumor-suppressive functions and can promote apoptosis via activating pro-apoptotic signaling pathways and inhibiting anti-apoptotic pathways." (PMID 37444578, 2023). "RASSF1 and 3 contain a SARAH-domain that intervenes in the regulation of MST1 and MST2 kinases in the activation of YAP, an activity crucial to its tumour suppressor function." (PMID 36765842, 2023). "As mentioned, MST1/2 are downstream effectors of the STRIPAK complex and are crucial regulators in the Hippo signalling pathway, known to exhibit a tumour-suppressive role by regulating cell growth, proliferation, and apoptosis." (PMID 38201504, 2023). "Conversely, the core kinase cassette of the Hippo pathway, which comprises MST1/2 and LATS1/2, has demonstrated tumor suppressive effects in several cancer types." (PMID 37251938, 2023). "Consistently, the MST1/2 inhibitor, XMU-MP-1, inhibited the activation of the Hippo pathway induced by UCMSCs-CM treatment and accordingly declined the anti-tumor effect of UCMSCs-CM on KGN cells." (PMID 36941685, 2023). "It was demonstrated that MST1, a tumor suppressor, is underexpressed in PDAC cells, which have a prominent role in tumor progression." (PMID 37893166, 2023). "Previous studies have also demonstrated the oncogenic roles of MST1/242 and LATS1/243 in human tumours, including proliferation, apoptosis, and glucose metabolism." (PMID 37665055, 2023). "These genes were KMT2C, MST1, HLA-A and BCL11A which are involved in epigenetic modifications, tumor suppression and immune surveillance." (PMID 35504960, 2022). "Phosphorylation of MST1 and LATS2 promoted by metallothionein 2A (MT2A) restrained the YAP1 nuclear localization, thereby preventing CRC from enhanced tumor growth and liver metastasis." (PMID 36289774, 2022).
tumor (continued). "In line with the negative regulation of MST1/2 on ZMYND8, this analysis also revealed that the expression levels of ZMYND8 were higher in oxaliplatin-treated tissues than in untreated tumor tissues." (PMID 35290241, 2022). "In the subcutaneous tumor samples, IHC staining showed that overexpression of MT2A promoted the expression of phosphorylated MST1 and YAP1 compared to the control." (PMID 35642057, 2022). "In addition to extracellular stress, here we showed that STRIPAK could also respond to genotoxic stress as a result of its dynamic assembly and active tuning of the MST1/2 kinases, which ultimately regulate nuclear DNA repair and tumor cell sensitivity to anticancer therapies." (PMID 35290241, 2022). "MST1/2 and LATS1/2 (upstream core kinases components) are important tumour-suppressors of the Hippo pathway." (PMID 36552980, 2022). "They found that miR-3910 directly inhibits the expression of MST1, promoting the growth and migration of HCC cells in vitro and tumor formation in vivo through the activation of oncogenic YAP." (PMID 33808155, 2021). "As shown in the boxplot, IL1B, MST1, GBP1, and NLRP3 were downregulated, and the other 35 PRGs were upregulated in tumor tissues." (PMID 34869364, 2021). "Mst1 mRNA levels were significantly higher in KB1P tumors, but Mst1r levels (measured by primers that identify all isoforms) were the same between tumor models." (PMID 32484599, 2020). "The upstream components of the Hippo-pathway including MST1/2, LATS1/2, NDR1/2, Merlin, and RASSFs have been identified to be tumor suppressors." (PMID 32174922, 2020). "Focusing on a limited set of Hippo core components, we found that both +DDR/+COL1 tumours displayed a significant downregulation of MST2, while +DDR1b tumours also showed reduced levels of LATS1 and MST1." (PMID 32047176, 2020). "BMP-2 treatment activates the Hippo kinase cascade, which includes mammalian Ste20-like kinase 1 (MST1), MOB kinase activator 1 (MOB1), and YAP (inactivation), and this action is tumor suppressive." (PMID 32731498, 2020). "Of note, MST1/2 and LATS1/2, the upstream kinases of the Hippo pathway, can regulate YAP phosphorylation as tumor suppressors." (PMID 30961610, 2019). "In a quantitative PCR study based on the expression of all Hippo pathway elements in CRC, the mRNA levels of MST1 and LATS2 in CRC tissues decreased more than those in colorectal cancer adenomas or adjacent non-tumor tissues." (PMID 30961610, 2019). "This complex inactivates the kinase Hippo/MST1 by methylation, which in turn allows the MST1 substrate YAP1 to relocate to the nucleus and activate a number of target genes promoting tumor metastasis." (PMID 30311405, 2019). "A recent study showed that overexpression of RASSF1 in HCC cells induced autophagy via inhibiting PI3K-AKT-mTOR signaling through the Hippo pathway module MST1 and suppressed HCC tumor growth." (PMID 31409760, 2019). "Phosphorylated HER3 Tyr1307 is able to induce MST1 methylation at the lys59 site, thereby producing active YAP/TAZ in tumor cells, thereby promoting metastasis in bone cancer." (PMID 30961610, 2019). "The knockdown of MST1, MST2, and SAV has been demonstrated to induce tumor formation in the liver of mice, emphasizing the pivotal function of YAP signaling in the initiation of HCC." (PMID 30961610, 2019). "The MST1/2-Lats-YAP/TAZ signaling pathway has potent effects on regulating cell proliferation, and was accepted as a potential mechanism of tumor growth." (PMID 29896440, 2018). "MST1/2 and LATS1, the most upstream proteins in the Hippo signalling pathway, act as tumour suppressors of human cancers." (PMID 28782275, 2018). "Firstly, the expression levels of MST1 and LATS1 were examined in both non-tumor tissues and PTC tissues." (PMID 30237435, 2018).
tumor (continued). "For instance, MST1/2 and LATS1/2, the upstream kinases of the Hippo pathway, function as tumour suppressors in multiple human cancers." (PMID 28782275, 2018). "For example, hepatocyte-specific deletion of MST1/2 in mice resulted in YAP activation, leading to significantly enlarged livers and tumor development by the age of five to six months." (PMID 30463366, 2018). "MST1 serine-threonine kinase, a component of the RASSF1-LATS tumor suppressor network, binds androgen receptor (AR), but the kinase activity of MST1 is not involved in inhibition of AR." (PMID 22035226, 2011). "As a primary active constituent of S. miltiorrhiza, salvianolic acid B has demonstrated anti-tumor potential in various studies.Salvianolic acid B elevates p-MST1 and p-YAP, blocking cell proliferation and migration driven by TGF-β1 and MST1/2 inhibitor XMU-MP-1." (PMID 39972480, 2025). "However, in specific tumor types, high RASSF4 expression paradoxically promotes tumor growth by interacting with mammalian sterile 20-like kinase 1 (MST1) to inhibit the Hippo signaling pathway." (PMID 41007433, 2025). "The treatment of AZD9291 alone did not affect BRD4, APT1, YAP1, and p-YAP1 and MST1 palmitoylation in tumor cells, whereas the treatment of NHWD870 alone reduced the expression of BRD4, APT1 and YAP1 but enhanced YAP1 phosphorylation and MST1 palmitoylation." (PMID 41184230, 2025). "Additionally, NEK2 inactivates the Hippo pathway by dephosphorylating MST1/2, further increasing YAP levels and contributing to tumor progression." (PMID 41256331, 2025). "Notably, this pathway can be reversed by activating YAP1 through MST1/2 inhibition, which shifts macrophages from an M2 to an M1 phenotype, enhancing CD8+ T-cell activity and mitigating tumor progression." (PMID 40330466, 2025). "Unfortunately, targeting Hippo core kinase components MST1/2 or LATS1/2 is not a viable option as this would promote tumor development." (PMID 40869130, 2025). "MST1, the ligand for MST1R, was also elevated at the mRNA level in tumor samples." (PMID 38212428, 2024). "Considering the well-characterized tumor suppressor function of the MST1/2 kinases, it is conceivable that DSF may eventually inhibit GC growth through reactivation of MST1/2." (PMID 38657866, 2024). "The data further showed that nevadensin could induce Yap degradation by phosphorylating and activating the MST1/2-LATS1/2 pathway and Merlin, thus affecting the proliferation of tumor cells." (PMID 37243813, 2023). "STING agonists induced dissociation of PP2A from MST1/2 in normal macrophages, but not in tumor conditioned macrophages." (PMID 36757811, 2023). "As the disease progresses from androgen-dependent to castrate-resistant, a decrease in both MST1 and PTEN tumor suppressor levels enhances AKT1 activity, thus linking MST1 loss with the phosphoinositide 3-kinase/protein kinase B (PI3K/AKT) pathway activity in driving disease progression." (PMID 35954292, 2022). "Driver gene alteration status (Altered or Unaltered) was used to stratify tumor samples, and the difference in means of MST1R and MST1 expression individually were compared across Altered/Unaltered status using samples from the TCGA PanCan and METABRIC datasets." (PMID 35626096, 2022). "Importantly, targeting the STRIPAK assembly with each of 3 distinct peptide inhibitors efficiently recovered the kinase activity of MST1/2 to suppress DNA repair and resensitize cancer cells to PARP inhibitors in both animal- and patient-derived tumor models." (PMID 35290241, 2022). "In the present study, increased expression of phosphorylated Mst1, LATS2 and YAP1 was observed in CRC cells overexpressing MT2A, and similar results were also observed in subcutaneous CRC tumor and liver metastasis tissues overexpressing MT2A according to immunohistochemical staining." (PMID 35642057, 2022). "Combined deletion of MINK1 and MST1/2 could inhibit the activation of LATS1/2, improve tumor immunogenicity, and inhibit tumor growth." (PMID 36303542, 2022).
tumor (continued). "SIRPγ bridged MST1 and PP2A to facilitate MST1 dephosphorylation, resulting in Hippo/YAP activation and leading to cytokine release by CSLCs, which stimulated CD47 expression in LUAD cells and consequently inhibited tumor cell phagocytosis." (PMID 35229723, 2022). "Given the known association between YAP activation and cancer, previous studies with MST1/2 inhibition included long-term administration without evidence of neoplasia." (PMID 35763355, 2022). "We first investigated the methylation of all the promoters of the genes involved in the RASSF/Hippo pathway, specifically RASSF1/2, STRK4/3 (coding for MST1 and MST2 proteins respectively), and LATS1/2, by MS-PCR using DNA extracted from the tumour blocks of 100 patients." (PMID 34885067, 2021). "The markedly increased protein expression of MST1, p-LATS1, p-YAP, and YAP (cytoplasm) and the significantly decreased expression of HIF-1α, TAZ, YAP (cells), and YAP (nucleus) in the tumor tissues of the sh-GHET1 group were compared with those of the sh-NC group." (PMID 33869194, 2021). "It is tempting to speculate that RASSF1A mimetics could be a treatment for tumours harbouring this oncogene while taking into account that BRAFV600E binds and inhibits MST1/2 in cancer cell lines." (PMID 31963420, 2020). "RAS bound with RASSF5, activate MST1/235,44 to form STK3/MST2 and STK4/MST1 complexes in the hippo signaling pathway that plays a crucial role in tumor suppression by limiting proliferation and stimulating apoptosis where SAV1, MOB1A/B act as effector molecules." (PMID 32884013, 2020). "However, the difference was not statistically significant, indicating that the bulk of the in vitro and in vivo tumor growth from WBP2-WT and MST1-K59R co-expression were contributed by WBP2." (PMID 32820148, 2020). "In addition, the protein levels of Rassf1, Mst1, Mst2, Sav1, Mob1, and p-Mob1 were increased, whereas those of YAP and CTGF were diminished in UA-treated xenograft tumor tissues." (PMID 31547587, 2019). "Staining of our TMA for macrophage infiltration did not however find any significant differences, and had no prognostic value, while serum levels of MST1 also showed no significant alterations between unaffected vs. tumor patients." (PMID 30863365, 2019). "MST1 and MST2 are the core kinases of mammalian Hippo tumor suppressor pathway, which complex and context-dependent regulatory mechanisms in health and disease still remain unclear." (PMID 30903103, 2019). "Organ-specific double knockout of MST1/2, e.g., in the liver has been shown to lead to tumor growth, because of the lack of constraints on cellular proliferation in these mice driven by the Hippo-YAP pathway." (PMID 31676778, 2019). "Functionally, these Mst1-knockout CTLs display enhanced cytotoxicity against tumour cells in vitro and greater suppression of tumour growth in vivo in a mouse thymoma (EG7-OVA) tumour model." (PMID 29597279, 2018). "Using these MOB1 variants with selective loss-of-interaction, we found that a stable interaction of MOB1 with LATS1/2, but not with MST1/2, is essential for tumor suppressive properties of MOB1 in human cancer cells." (PMID 28947795, 2017). "The transcriptional coactivator YAP is a major downstream negative effector of the Hippo pathway 6, 7 and is tightly negatively regulated by a series of upstream components such as NF2, LATS1/2, MST1/2 and SAV1, which are tumour suppressors in several types of human cancers." (PMID 28470935, 2017). "Thus, MST1/2 and LATS1/2 would be tumour suppressors that negatively regulate by direct phosphorylation YAP1, which would behave as an oncogene." (PMID 27322327, 2016).